DOCK1 (dedicator of cytokinesis 1)
Diseases named in the same sentence as DOCK1 in open-access papers (continued):
Sharing a sentence is not in itself a finding about the gene and the disease.
melanoma (4 papers, 2016 to 2025). A malignant, usually aggressive tumor composed of atypical, neoplastic melanocytes. "The DOCK1 depletion-induced increase in claudin-1 inhibited cell migration and induced caspase activation and cell death, which is consistent with the previous finding that re-expression of claudin-1 causes cell apoptosis in TNBC and modulates the mobility of melanoma cells." (PMID 31717460, 2019).
triple-negative breast carcinoma (4 papers, 2022 to 2026). An invasive breast carcinoma which is negative for expression of estrogen receptor (ER), progesterone receptor (PR), and human epidermal growth factor receptor 2 (HER2). "A recent study reported that DOCK1 inhibition leads to suppressed migration of the triple-negative breast cancer cell lines MDA-MB-157 and MDA-MB-231." (PMID 36627894, 2022). "Elevated DOCK1 expression enhances tumor cell migration via pathways involving RRP1B and Claudin-1, particularly in claudin-low and triple-negative breast cancer cells." (PMID 41516402, 2026).
asthma (3 papers, 2008 to 2021). "DOCK1 (Dedicator of cytokinesis 1 [MIM 601403]) was reported to be moderately associated with asthma." (PMID 23829686, 2013). "Inversely, minor alleles DOCK1_rs1051039G, PTPRE_rs4369314A and PTPRE_rs7081735G were undertransmitted to the asthmatic probands, suggesting a protective effect of these alleles for asthma (0.010<p<0.049)." (PMID 18682798, 2008). "Among these, five (LPA, ADAM8, DOCK1, GPR123 and PTPRE) presented modest associations with asthma, atopy or allergic asthma." (PMID 18682798, 2008).
colon cancer (3 papers, 2020 to 2024). "Mechanistically, CTTN increases accumulation of DOCK1 and Rac1, and DOCK1 silencing partially abolishes the migration and invasion capacity induced by CTTN in SW480 colon cancer cells." (PMID 32178475, 2020).
leukemia (3 papers, 2017 to 2025). A malignant (clonal) hematologic disorder, involving hematopoietic stem cells and characterized by the presence of primitive or atypical myeloid or lymphoid cells in the bone marrow and the blood. "This was consistent with previous study in which knock down of ELMO1, the partner gene of DOCK1, resulted in reduced chemotaxis of leukemia cells." (PMID 29069784, 2017). "HOPX, DOCK1, DNMT3B, MMRN1, and ARHGAP22 genes were reported as important leukemia stem cell markers." (PMID 33225420, 2021).
liver cancer (3 papers, 2022 to 2024). An epithelial or non-epithelial malignant neoplasm that arises from the liver. "Taken together, these results indicated that DOCK1 expression levels determine the sensitivity of liver cancer cells to metformin." (PMID 35217990, 2022). "Relative expression analysis of DOCK1 in liver cancer samples from The Cancer Genome Atlas (TCGA) showed the same results." (PMID 35217990, 2022). "Our findings also suggest the potential effectiveness of a metformin-DOCK1 inhibitor combination strategy for treating liver cancer patients with high DOCK1 expression, which warrants further clinical investigation." (PMID 35217990, 2022). "Mechanistically, metformin facilitates the activation of RAC1 by phosphorylating DOCK1, which in turn attenuates the anti-tumor effects of metformin, leading to the observed unresponsiveness in liver cancer." (PMID 35217990, 2022). "In conclusion, our study highlights the role of DOCK1 in determining the response of liver cancer cells to metformin treatment and illustrates the inhibition of tumor progression by metformin in liver cancer patients with low DOCK1 expression." (PMID 35217990, 2022). "Collectively, our data demonstrated that treatment with TBOPP, a DOCK1 inhibitor, results in a strong synergistic effect with metformin in suppressing liver cancer in several models both in vitro and in vivo." (PMID 35217990, 2022). "As the most frequently prescribed anti-diabetic drug, metformin has a demonstrated record of safety, and therefore the identification of different subtypes of liver cancer patient may provide an expanded range of options for patients with low DOCK1 expression." (PMID 35217990, 2022). "Collectively, these results indicated that DOCK1 levels regulate the strength of metformin’s anti-tumor effects on liver cancer, while suppression of DOCK1 sensitizes liver cancer to metformin in both patient-derived HCC organoids in vitro and mouse models in vivo." (PMID 35217990, 2022). "Collectively, our findings demonstrate that DOCK1 levels largely determine whether metformin will be an effective therapy for individual HCC patients, and that DOCK1 targeting is a promising strategy for sensitizing liver cancer cells to metformin." (PMID 35217990, 2022). "Based on these findings, we thus propose the possibility of rational use of metformin in personalized therapeutic strategies against liver cancer that depend on patient levels of DOCK1, with low DOCK1 levels indicating the potential for benefit from metformin administration." (PMID 35217990, 2022). "Furthermore, analysis of several datasets showed that DOCK1 is upregulated in liver cancer, which suggested that the combined treatment of metformin with DOCK1 inhibitor could provide clinical benefits for HCC patients who have high levels of DOCK1." (PMID 35217990, 2022). "Finally, we sought to determine whether DOCK1 expression levels could serve as a potential biomarker for evaluating the therapeutic effectiveness of metformin in liver cancer patients by retrospective evaluation of 122 clinical HCC patients with diabetes." (PMID 35217990, 2022). "Correlation analysis revealed that DOCK1 expression had the highest Pearson correlation coefficient with IC50 values and AUC scores of metformin, which suggested that DOCK1 levels may contribute to determining the sensitivity of liver cancer cells to metformin." (PMID 35217990, 2022). "The DOCK1-selective inhibitor, TBOPP, potentiates anti-tumor activity by metformin in vitro in liver cancer cell lines and patient-derived HCC organoids, and in vivo in xenografted liver cancer cells and immunocompetent mouse liver cancer models." (PMID 35217990, 2022). "In addition, the effects of metformin and DOCK1 were not investigated in liver cancer patients without diabetes." (PMID 35217990, 2022).
liver cancer (continued). "Specifically, we revealed that DOCK1 inhibition by shRNAs or TBOPP, a DOCK1 selective inhibitor, suppressed metformin-induced RAC1 activation, thus enhancing the anti-tumor effects of metformin in both patient-derived organoids and mouse models of liver cancer." (PMID 35217990, 2022).
lung carcinoma (2 papers, 2020 to 2023). "A recent study established DOCK1 as an important regulator of macropinocytosis in lung cancer cells, and interestingly, a pharmacological inhibitor of DOCK1 displayed significant anti-invasive and anti-metastatic properties." (PMID 32158759, 2020).
abortion (1 paper, 2024). the ending of pregnancy by removing a fetus or embryo before it can survive outside the uterus. "In this study, we found DOCK1 expression is decreased in the placental villi of patients with recurrent spontaneous abortion, and that its expression determined the invasive properties of extravillous trophoblasts (EVTs), highlighting a previously unknown role of DOCK1 in regulating EVT function." (PMID 37967942, 2024).
acral melanoma (1 paper, 2023). "Recently, CRK‐Like (CRKL) was found to be amplified in acral melanoma, where its protein product is bound to DOCK1 and DOCK5." (PMID 36271211, 2023).
acute promyelocytic leukemia (1 paper, 2017). An aggressive form of acute myeloid leukemia (AML), characterized by arrest of leukocyte differentiation at the promyelocyte stage, due to a specific chromosomal translocation t(15;17) in myeloid cells. "The similar prognostic impact of DOCK1 expression was also present in the patients with AML other than acute promyelocytic leukemia as well as cytogenetically normal AML in our cohort." (PMID 29069784, 2017).
Cachexia (1 paper, 2020). Severe weight loss, wasting of muscle, loss of appetite, and general debility related to a chronic disease. "Another major network centered around Dedicator of Cytokinesis 1 (DOCK1) (a 312-gene network), a Rho guanosine triphosphatase (GTPase)-related gene regulated by mechanical strain and genetically linked to cachexia." (PMID 32755574, 2020).
cognitive decline (1 paper, 2021). "DOCK1 was an AD-associated gene in a module of polygenic risk scores associated with astrocyte, language, and cognitive decline." (PMID 34440432, 2021).
cyst (1 paper, 2017). A sac-like closed membranous structure that may be empty or contain fluid or amorphous material. "However, cyst-lining epithelial cells in Pkd1-deficient kidneys showed reduced and disorganized actin cytoskeletons with significantly decreased levels of marker genes such as Wasf2, Dock1, and Itga4." (PMID 29074972, 2017). "We observed that Dock1 repression also stimulated cyst development via alterations of the actin structure in mIMCD 3D cultures." (PMID 29074972, 2017). "In addition, knocking down Wasf2, Dock1, or Itga4 promoted cyst growth with actin cytoskeleton defects in 3D culture conditions." (PMID 29074972, 2017). "However, miR-182-5p inhibition could not slow cyst growth in Pkd2f/f:Aqp2-cre mice because Wasf2, Dock1, and Itga4 play significant roles in Pkd1 but not in Pkd2 conditional KO mice." (PMID 29074972, 2017).
dementia (1 paper, 2023). Loss of intellectual abilities interfering with an individual's social and occupational functions. "Importantly, five of these pre-mRNAs (DOCK1, HOMER1, MAN2A1, RTN4, and ST18) were also found to correlate with dementia severity in the parietal cortex, suggesting that these circRNAs in general correlate with AD progression." (PMID 37266374, 2023).
endometrial carcinoma (1 paper, 2024). A malignant tumor arising from the epithelium that lines the cavity of the uterine body. "In this work, we discovered that the expressions of DOCK1 in endometrial carcinoma tissues and cells were higher than that in adjacent tissues and normal endometrial cells." (PMID 38438882, 2024). "Immunohistochemical technique was utilized to determine the DOCK1 protein expression in endometrial carcinoma tissues and adjacent normal endometrial tissues." (PMID 38438882, 2024). "CCK-8, BrdU, transwell and flow cytometry were performed to analyze the effect of DOCK1 expression changes on the viability, proliferation, invasion, migration and apoptosis of endometrial cancer cells, respectively." (PMID 38438882, 2024). "DOCK1 expression was increased in endometrial cancer tissues and cells compared with those in normal adjacent tissues and cells." (PMID 38438882, 2024). "DOCK1 expression was upregulated in endometrial cancer tissues in contrast to adjacent normal endometrial tissues (P < 0.05)." (PMID 38438882, 2024). "Consequently, the inhibition of DOCK1 weakened the growth and induced the apoptosis of endometrial carcinoma in vivo." (PMID 38438882, 2024). "Hence, the present study explored the molecular mechanism of DOCK1 in regulating biological behavior of endometrial cancer and hopes to provide a new direction and theoretical basis for the early diagnosis and potential treatment of endometrial cancer." (PMID 38438882, 2024). "Additionally, the treatment of Raf inhibitor LY3009120 partly inhibited the effect of DOCK1 on the malignant biological behavior of endometrial cancer." (PMID 38438882, 2024). "The results suggested that DOCK1 might mediate c-Raf/ERK pathway via regulating the activity of Rac1 to involve in regulating endometrial cancer malignancy." (PMID 38438882, 2024). "In this study, DOCK1 could promote the migration and invasion of endometrial cancer cells through decreasing E-cadherin expression and upregulating MMP9 and Ezrin expressions." (PMID 38438882, 2024). "DOCK1 could enhance the malignant biological behavior of endometrial cancer cells, which might be through c-RAF/ERK1/2 signaling pathways in vitro and in vivo." (PMID 38438882, 2024). "DOCK1 knockout could inhibit the malignant biological behavior of endometrial cancer cells, while DOCK1 overexpression played the opposite effect." (PMID 38438882, 2024). "Hence, DOCK1 might mediate c-Raf/ERK signaling pathway via Rac1 activation to modulate malignancy of endometrial cancer." (PMID 38438882, 2024). "The effect of DOCK1 gene on the biological behavior of endometrial carcinoma cells and its related pathway has not been reported." (PMID 38438882, 2024). "However, few studies investigated the function and mechanism of DOCK1 in gynecological cancers, and no research has been reported in endometrial cancer so far." (PMID 38438882, 2024).
hepatocellular carcinoma (1 paper, 2024). A malignant tumor that arises from hepatocytes. "Interference with circ-DOCK1 (circ_0020397) inhibits hepatocellular carcinoma cell proliferation, invasion and migration via the miR‐654‐5p/SMAD2 axis." (PMID 38570856, 2024).
Immunodeficiency (1 paper, 2022). Failure of the immune system to protect the body adequately from infection, due to the absence or insufficiency of some component process or substance. "DOCK1 is the gene encoding dedicator of cytokinesis, and a study has shown that expression loss of DOCK1 could lead to immunodeficiency." (PMID 35491409, 2022).
intracranial aneurysm (1 paper, 2021). "The circRNA dedicator of cytokinesis 1 (circ_DOCK1, also called hsa_circ_0020397 according to the circRNA ID of circBase database) is downregulated in artery wall tissues and vascular smooth muscle cells of intracranial aneurysm patients, and it promotes vascular smooth muscle cell proliferation." (PMID 34109173, 2021). "This study proposed the importance of circ_DOCK1/miR-409-3p/MCL1 axis in regulating HBVSMC dysfunction and provided a potential therapeutic target for intracranial aneurysm treatment." (PMID 34109173, 2021).
non-small cell lung carcinoma (1 paper, 2025). A group of at least three distinct histological types of lung cancer, including non-small cell squamous cell carcinoma, adenocarcinoma, and large cell carcinoma. "In terms of drug resistance, previous studies have demonstrated that enoxaparin sensitizes human non-small-cell lung carcinomas to Gefitinib by inhibiting DOCK1 expression." (PMID 38415469, 2025).
Obesity (1 paper, 2021). Accumulation of substantial excess body fat. "The DOCK1 gene, an atypical Rac activator, has been associated with obesity in a Yup’ik population and is required for cardiovascular development." (PMID 34572079, 2021).
periodontitis (1 paper, 2022). An acute or chronic inflammatory process that affects the tissues that surround and support the teeth. "During the inflammatory response of periodontitis, the lymphocytes, macrophage and neutrophils are regulated by expression of multiple genes, such as ARHGAP10, ARPC1B, DOCK1, FGF2/4, TNFRSF1B, NXT1, and AHR, all of which were identified in our analysis." (PMID 35491409, 2022).
polycystic ovary (1 paper, 2020). "DOCK1 has been suggested to be involved in polycystic ovarian syndrome, due to its downregulated expression in polycystic ovary." (PMID 32973865, 2020).
Yersinia infection (1 paper, 2024). "The other was “Yersinia infection, oas05135”(p = 0.078788), containing 5 genes (MAP3K7, PXN, DOCK1, LOC101103376, and LOC101103623) and is also associated with immunity." (PMID 38333624, 2024).
tumor (27 papers, 2009 to 2026). "To explore how DOCK1 deficiency enhances the anti-tumor effects of metformin, we performed RNA-seq analysis in PLC cells expressing NTC or shDOCK1 (PLC-NTC, PLC-shDOCK1 cells) in the presence or absence of metformin." (PMID 35217990, 2022). "Since RAC1 has been shown to play a major role in cytoskeleton assembly, tumorigenesis and tumor proliferation, we thus hypothesized that DOCK1 deficiency sensitizes cancer cells to metformin via inhibition of RAC1 activation." (PMID 35217990, 2022). "CircDOCK1, derived from mRNA DOCK1, exhibits varying roles in tumor initiation and progression across distinct cancer types." (PMID 39967686, 2025). "Here, through a genome-wide CRISPR-Cas9-based knockout screen, we find that DOCK1 levels determine the anti-tumor effects of metformin and that DOCK1 is a synthetic lethal target of metformin in HCC." (PMID 35217990, 2022). "Clinically, our results suggest the potential implication to determine DOCK1 levels by immunohistochemical analysis of tumor tissues from patient biopsy." (PMID 35217990, 2022). "Quantitative analysis of DOCK1 immunohistochemistry staining in HCC specimens indicated that DOCK1 was upregulated in tumor tissues compared to that in adjacent normal tissue." (PMID 35217990, 2022). "Further immunohistochemical staining revealed consistent expression of DOCK1 in all four organoids and their corresponding tumor tissues." (PMID 35217990, 2022). "Cumulatively, these data demonstrated that DOCK1 levels determine the anti-tumor effectiveness of metformin in HCC patients." (PMID 35217990, 2022). "Even though DOCK1 has been reported to be a tumor promoter in a wide spectrum of human cancers, the relationship between AML and DOCK1 has not been fully explored in the literature." (PMID 33658535, 2021). "Tumor volume and weight were markedly declined in the sh-circ_DOCK1 group in comparison to the sh-NC group." (PMID 33685455, 2021). "On top of that, the pearson correlation analysis revealed a significant relationship between LINC00665 and DOCK1 in AML tumor samples." (PMID 33658535, 2021). "The migration and invasion of many tumor cells is related to the upregulation of DOCK1, and DOCK1 can reverse the inhibition of IκBα phosphorylation." (PMID 33841156, 2021). "MiR-486-5p is a microRNA that known to function as a tumor suppressor, and bioinformatics analysis predicts that Dock-1 has a binding site of miR-486-5p." (PMID 31528235, 2019). "Western blot analysis confirmed the overexpression of YAP1 and knockdown of DOCK1 in tumor tissues." (PMID 35217990, 2022). "Here, we found that knockdown of DOCK1 inhibited tumor development in YAP5SA induced orthotopic HCC model, suggesting that DOCK1 might directly regulate HCC development." (PMID 35217990, 2022). "In addition, mouse xenograft experiments using PLC cells with DOCK1 knockdown showed that suppression of DOCK1 resulted in potentiation of the anti-tumor effects of metformin." (PMID 35217990, 2022). "Further, overexpression of DOCK1 eliminated the anti-tumor effects of metformin in Huh7 cells." (PMID 35217990, 2022). "Our data showed that DOCK1 deficiency resulted in sensitization of the patient-derived HCC organoids to metformin, while metformin combined with TBOPP showed strong, synergistic anti-tumor effects in metformin-resistant organoids." (PMID 35217990, 2022). "Genes other than CLDN1, CLDN3, CLDN4, CLDN7, and ZO1 may also be coordinately regulated by DOCK1 and may contribute to tumor growth, but this remains to be investigated." (PMID 31717460, 2019). "Western blot analysis of tumor tissue lysates revealed that TBOPP treatment obviously suppressed the metformin-induced RAC1 activation, which confirmed that RAC1 activation contributes to the DOCK1 suppression associated sensitization of cancer cells to metformin in vivo." (PMID 35217990, 2022).